FGL2 (fibrinogen like 2)
Diseases named in the same sentence as FGL2 in open-access papers (continued):
Sharing a sentence is not in itself a finding about the gene and the disease.
tumor (continued). "Patients showing high FGL2 expression had significantly large tumours (P = 0.002), high T classification (P = 0.002), and high TNM stage (P = 0.003)." (PMID 28978925, 2017). "Fibrinogen-like protein 2 (FGL2) is highly expressed in various tumour tissues and plays a vital role in tumour initiation and progression." (PMID 28978925, 2017). "Next, we evaluated FGL2 expression pattern in 170 paraffin-embedded ccRCC tumour tissues and 40 peritumoural renal tissues by performing immunohistochemical analysis." (PMID 28978925, 2017). "FGL2 mRNA expression was significantly higher in tumoural tissues than in peritumoural tissues (P < 0.001)." (PMID 28978925, 2017). "Gene expression analyses of human tumor samples will be necessary to identify cancers where FGL2 is overexpressed and is inhibiting host anti-cancer immunity." (PMID 26241231, 2015). "The FGL2–FcγRIIB pathway is also known to be utilized by viruses and tumor cells to evade immune surveillance." (PMID 26241231, 2015). "It has previously been reported that FGL-2 was detected in tumor tissues being upregulated in cancer cells and interstitial inflammatory cells, whereas the normal tissue surrounding the tumor did not display overexpression of FGL-2." (PMID 25303152, 2014). "Recently, it was reported that knock down of FGL-2 delayed tumor growth and angiogenesis in mice injected with human hepatocellular carcinoma cell line." (PMID 25303152, 2014). "Previous studies have reported that FGL-2 was detected in tumor tissues, being overexpressed in the tumor and interstitial inflammatory cells." (PMID 25303152, 2014). "Because macrophages are known to express membrane-bound Fgl2 as well as sFgl2, the ability of macrophages to secrete sFgl2 (which binds to FcγRIIB) was assessed through isolation of CD11b+ cells from naive spleen, tumor-challenged spleen, or tumor of WT mice." (PMID 40125553, 2025). "Macrophages from tumor-challenged mice secrete Fgl2 and most at the tumor." (PMID 40125553, 2025). "As macrophages compose a large portion of tumor-infiltrating cells, we then asked whether macrophages could express Fgl2 at the tumor in mice." (PMID 40125553, 2025). "Furthermore, in patients with SKCM, Fgl2 expression was positively correlated with macrophage infiltration into the tumor." (PMID 40125553, 2025). "As the role of tumor-derived Fgl2 has been described, we sought to determine whether the tumor was a major cellular source of Fgl2 in our model." (PMID 40125553, 2025). "However, WT OT-I were preferentially increased at the tumor compared with Fcgr2b–/– OT-I in Fgl2–/– hosts compared with WT hosts." (PMID 40125553, 2025). "Lastly, we sought to determine whether Fgl2 secreted by CD11b+ isolated from tumor-challenged mice was sufficient to induce apoptosis of FcγRIIB-competent but not Fcgr2b–/– OVA-specific CD8+ T cells." (PMID 40125553, 2025). "Additionally, FGL2 are involved in complex tumor invasion and cell migration processes, which can lead to more aggressive tumor phenotypes and poorer patient prognosis." (PMID 39629005, 2024). "Targeting the FGL2-FcγRIIB pathway could potentially be a groundbreaking approach in tumor immunotherapy." (PMID 38816776, 2024). "Moreover, the methylation level of FGL2 was significantly increased in BLCA patients with advanced tumor stage and lymph node metastasis." (PMID 38903931, 2024). "As absence of FGL2 reduced tumour burden in both models, we next sought to determine whether FGL2 normally enhances tumour progression by inducing immune cell changes in the TME." (PMID 38191799, 2024). "Similar to FGL1, FGL2 plays opposite roles in different tumor types." (PMID 38903931, 2024). "Based on these data, we can speculate that cells co expressed with FCGR3A and FGL2 migrate from peripheral blood into the tumor." (PMID 39629005, 2024). "In parallel, we assessed how FGL2 may influence tumour development of a more immunogenic tumour model, B16F10." (PMID 38191799, 2024).
tumor (continued). "The FGL2-deficient mice failed to develop tumor, suggesting that FGL2-mediated antigen presentation does not seem to successfully activate the anti-tumor effect of T cells." (PMID 39629005, 2024). "In this study, we found that under chronic inflammatory conditions, antigen-specific PD-1+ CD8+ T cells can secrete the immunoregulatory cytokine fibrinogen-like protein 2 (Fgl2) that regulates the antigen-specific CD8+ T cell response to tumor and virus in a cell-autonomous manner." (PMID 38902261, 2024). "Our previous studies believe that FGL2 is synthesized from tumor cells and immune cells." (PMID 39629005, 2024). "Indeed, FGL2-specific polyclonal antibodies induce antitumor activity against GBM tumor cells in syngeneic mouse models." (PMID 36759517, 2023). "Indeed, overexpression of FGL2 in tumor cells and milieu have been related to increased proliferation and metastasis (either directly or mediated via generation of thrombin)." (PMID 37200306, 2023). "Especially, FGL2 which was upregulated in MSI CRC and BRAF-mutated CRC could lead to high tumor mutation burden." (PMID 38036953, 2023). "There are multiple reports that FGL2 supports tumor development and metastasis." (PMID 37200306, 2023). "In metastasis CRC versus controls, two pivotal negative correlated miRNA-mRNA regulatory pairs (miR-20a-5p/ FGL2 and miR-139-5p/ STC1) could be considered to associate with tumor metastasis in CRC." (PMID 38036953, 2023). "Moreover, accumulating evidence established the significance of FGL2 in the biology of cancer by supporting tumor development and metastasis." (PMID 37200306, 2023). "Since FGL2 can act on antigen-presenting cells and inhibit the anti-tumor activity of T cells, it may be a future direction to try to apply FGL2 targeting therapy to GBM treatment." (PMID 36313679, 2022). "FGL2 secreted by GSCs is thought to activate tumor-infiltrating immune cells." (PMID 36313679, 2022). "FGL2 expression in GIST was associated with the low‐risk category of the National Institutes of Health risk stratification scheme, a low cell proliferation rate, small tumour size and favourable RFS in clinical patient series." (PMID 35029030, 2022). "And a small amount of FGL2 expression in tumor tissues could significantly reduce the intensity of these CD103+DC-induced signals.This discovery may shed new light on the development of DC immunotherapy." (PMID 36313679, 2022). "Fgl2 expression in subcutaneous xenograft tumours was verified by IHC." (PMID 34975313, 2022). "In contrast, Fgl2 overexpression significantly enhanced the tumour volumes and growth rates." (PMID 34975313, 2022). "In addition, FGL2 overexpression can skew macrophages and other activated antigen-presenting cells (APCs) in the tumor microenvironment from an inflammatory (M 1) or neoplastic (M0) phenotype to an immunosuppressive (M2) phenotype." (PMID 36313679, 2022). "Meanwhile, FGL2 could promote the polarization of macrophages and the proliferation of Treg cells in tumor microenvironment, thus enhancing the immunosuppressive function." (PMID 33867830, 2021). "Moreover, in CAC, patients with FGL2 overexpression have a poor prognosis overall, and FGL2 overexpression probably accelerates tumor progression by inducing epithelial-macrophage transformation." (PMID 33867830, 2021). "Moreover, FGL2 also involves in tumor development 36, and has been perceived to the overexpression of FGL2 in tumor and interstitial inflammatory cells." (PMID 33867830, 2021). "Infiltrating immune cells and tumor cells may also secrete FGL2 to promote the polarization of TAMs into M2 macrophages, forming an important carcinogenic loop that promotes the initiation and progression of ESCA." (PMID 33323552, 2020). "So, we infer that FGL2 might activate CTLs functions to exert anti-tumor effects by stimulating APCs to bind naïve CD8+ T cells." (PMID 32206449, 2020).
tumor (continued). "We speculate that FGL2 is highly expressed in the tumor stroma, and that M2 macrophages in the tumor stroma secrete FGL2 to alter the TME." (PMID 33323552, 2020). "The paucity of anti-tumor immune responses may well be FGL2 produced by Tregs contributing in part to a reduction of tumor-infiltrating CD8+ T-cells." (PMID 33375291, 2020). "In conclusion, our results suggested that FGL2, which is highly expressed by M2 macrophages, could be considered as a tumor marker for early ESCA diagnosis and an effective immunotherapeutic target for ESCA treatment." (PMID 33323552, 2020). "However, the effects of FGL2 on the progression and tumor immunology of ESCA have yet to be reported." (PMID 33323552, 2020). "FGL2 is mainly expressed by activated endothelial cells, macrophages, T cells and tumor cells." (PMID 33323552, 2020). "Next, we used the Tumor IMmune Estimation Resource (TIMER) to assess whether FGL2, ERI1 or WNT5B expression correlated with infiltrating immune cell levels in ESCA." (PMID 33323552, 2020). "GSEA showed that FGL2 expression was positively correlated with enhanced tumor killing." (PMID 32206449, 2020). "Our results clearly show that FGL2 expressed by tumor cells reduces CD103+ DC differentiation." (PMID 30683885, 2019). "We discovered that FGL2 secreted from tumor cells is the primary suppressor of differentiation of antigen-presenting CD103+ DCs via blocking of granulocyte-macrophage colony-stimulating factor (GM-CSF) signal transduction and subsequent T cell functions in the brain." (PMID 30683885, 2019). "Similarly, tumor sizes in C57BL/6 mice bearing Hepa1–6 cells were significantly smaller in groups receiving anti-FGL2 treatment or harboring the Fgl2 knockout as compared with controls." (PMID 31409352, 2019). "Thus, expression of FGL2 in tumor cells prevents T cell priming by reducing the development of Batf3-dependent CD103+ DCs." (PMID 30683885, 2019). "To determine the effect of tumor-cell intrinsic FGL2 on tumor progression, we used complete FGL2 knockout (KO) tumor-cell lines and FGL2-deficient (FGL2−/−) mice to reveal a novel molecular immune mechanism for FGL2’s regulation of tumor progression in the CNS." (PMID 30683885, 2019). "Additionally, analysis of CD8+ T cells revealed that Fgl2 knockout elevated the number of tumor-infiltrated CD8+ T cells and their production of granzyme B in DLNs." (PMID 31409352, 2019). "Similarly, HCC patients had increased sFGL2 levels compared to CHB patients (P = 0.033) and FGL2 mRNA was up-regulated in tumor tissues compared to adjacent non-tumor tissues (P = 0.043)." (PMID 30419833, 2018). "FGL2 mRNA was quantified by qRT-PCR in 32 pairs of tumor and adjacent non-tumor liver tissues." (PMID 30419833, 2018). "Moreover, tumour size, T classification, TNM staging, Fuhrman grade, and high FGL2 expression were significantly associated with RFS (HR, 4.214; 95% CI, 2.119–8.383; P < 0.001)." (PMID 28978925, 2017). "Previous study indicated that FGL2 may serve as a therapeutic target or a biomarker for tumor early detection." (PMID 29069717, 2017). "This suggested that aberrant FGL2 expression in ccRCC interferes with tumour progression." (PMID 28978925, 2017). "Up to now, increased FGL-2 expression was reported within tumor cells." (PMID 25303152, 2014). "Furthermore, FGL2 also promote tumor immune evasion by directly blocking T-cell activation." (PMID 41252877, 2025). "Hence,we hypothesized that FGL2 could control the infiltration of anti-tumor immune cells, which might influence the formation and function of NETs and play a role in the prognosis of NB." (PMID 39575432, 2024). "Therefore, while NK cells in the absence of FGL2 have significantly higher markers of NK activation by flow cytometry, they do not significantly contribute to prolonged survival or reduced tumour burden in Fgl2−/− mice, suggesting that FGL2 had some NK cell-independent effects." (PMID 38191799, 2024).
tumor (continued). "Similarly, Fgl2 expression was observed in macrophages/monocytes and DCs, with minimal cancer cell expression found when analyzing datasets from lung, breast, and colorectal tumours." (PMID 38191799, 2024). "Therefore, the upregulation of FCGR3A and FGL2 expression is induced by the tumor." (PMID 39629005, 2024). "Overall, these results uncovered that FGL2 might be an important regulator in tumor immunity." (PMID 38903931, 2024). "However, FGL2 is also expressed in endothelial cells and macrophages, and FGL2 may also promote tumor angiogenesis by inducing value-added endothelial cells and recruiting inflammatory cells, this part needs to be further investigated." (PMID 36313679, 2022). "In turn, FGL2 may serve as a novel target for the intervention of tumor development." (PMID 36313679, 2022). "Furthermore, FGL2 prothrombinase could contribute to tumor hypercoagulability and presumably to angiogenesis." (PMID 33867830, 2021). "FGL2 shows prothrombin enzyme activity and plays immunomodulatory function in a diversity of diseases, including viral-induced inflammation, xenograft rejection, chronic obstructive pulmonary disease, autoimmune disorders 22, 23, abortion and tumor growth 24-27." (PMID 33867830, 2021). "So, FGL2 might promote GBM tumor progression by suppressing CD103+ dendritic cell differentiation." (PMID 32206449, 2020). "Furthermore, lymphocytes from tumor-draining lymph nodes (TDLNs) and spleens of FGL2KO tumor-bearing mice showed higher cytolytic activity against tumor cells than those from Ctrl tumor-bearing mice, indicating a heightened cytotoxic function of CD8+ T cells in mice with FGL2-deficient tumors." (PMID 30683885, 2019). "Mechanistic studies uncovered that Fgl2 KO impaired the immunosuppressive molecule CD47; reconstitution of CD47 expression in Fgl2-KO tumor cells reversed the protection." (PMID 41380903, 2025). "Ten Fgl2-KO primary and metastatic tumor cell lines, generated via CRISPR/Cas9, were used to vaccinate mice and for intracranial challenges with the WT tumor cells." (PMID 41380903, 2025). "Here the authors show, using mouse genetic tools and human patient samples, that CD8 T-derived Fgl2, an immunosuppressive cytokine, binds autologous FcγRIIB receptor to induce CD8 T cell apoptosis and dampen anti-tumor or antivirus immunity." (PMID 38902261, 2024). "In tumor-infiltrating exhausted CD8+ T cells, the immunosuppressive factor fibrinogen-like protein 2 (Fgl2) is expressed and positively regulated by FcγRIIB, which is the only inhibitory IgG-Fc receptor expressed in highly differentiated effector CD8+ T cells." (PMID 39342365, 2024). "The overexpression of FGL2 can induce epithelial–mesenchymal transition (EMT) and promote tumor progression." (PMID 38248651, 2023). "FGL2 has immunosuppressive effects in the GBM tumour microenvironment and the ability to promote the progression of malignant tumours, making it a potential new target gene for GBM immunotherapy." (PMID 37990103, 2023). "GADCs, along with FGL2 and CCL2 expressed by tumor cells and GAMs, also induce Tregs to suppress anti-tumor responses by inhibiting DC antigen presentation." (PMID 35711434, 2022). "Fibrinogen like protein-2 (FGL2) plays a key role in cancer by regulating the proliferation, invasion, and migration of tumor cells, or regulating the function of immune cells in the TME." (PMID 35602471, 2022). "The TCGA database showed that the expression of CD2, FGL2, LAT2, and SLAMF1 in tumor tissues was significantly lower than that in cancer tissues, which was confirmed by western blotting experiments." (PMID 35602471, 2022).
tumor (continued). "As predicted, disruption of the FGL2/PPBP paracrine loop through FGL2 knockout and anti-PPBP antibody binding significantly suppresses the tumorigenic effects of FGL2 and prolongs survival in tumour-bearing mice." (PMID 36555253, 2022). "CAPZA1, HLA-E, IMPA2, NFE2L3, PLEKHO1, SIGLEC1, and UBE2Z were expressed at higher levels in tumor tissues, whereas EMX2, FGL2, FUCA1, and GRB2 were expressed at lower levels in tumor tissues." (PMID 35127943, 2022). "Apart from FGL2 blocks TRAF6/TAK1/NF-κB/p38 signal and JAK2/STAT1/5 in response to GM-CSF, thereby restraining CD103 induction on DCs, thus stimulates the growth of tumor cells." (PMID 33867830, 2021). "In contrast, immune competent mice, including wild-type (WT) and FGL2‒/‒, survived after implantation of GL261-FGL2KO tumor cells." (PMID 30683885, 2019). "The same results were obtained in FGL2−/− mice prechallenged with GL261-FGL2KO cells, showing that tumor cell-specific FGL2KO is crucial to induce this systemic adaptive immune response." (PMID 30683885, 2019). "Univariate Cox regression analysis showed that tumour size, T classification, TNM staging, necrosis, and high FGL2 expression were independent predictors of OS (HR, 6.636; 95% CI, 2.579–17.080; P < 0.001)." (PMID 28978925, 2017). "We show that this reduced response is due to immune cell–derived and not tumor-derived Fgl2 that regulates FcγRIIB+CD8+ T cells." (PMID 40125553, 2025). "Instead, cells originating from the host present at the tumor but not the tumor itself are predominant sources of Fgl2." (PMID 40125553, 2025). "FcγRIIB+ Fgl2+ CD8+ did not persist as we found significantly decreased frequencies of these double positive cells at day 21 compared to day 14 of tumor progression." (PMID 38902261, 2024). "CD31 acts as a co-inhibitory receptor, where CD31+ DCs are more tolerogenic, suggesting in the absence of FGL2 cDC2s in B16F10 tumours are more activated (MHCII+, CD86+, CD40+) and less immunosuppressive (CD31+)." (PMID 38191799, 2024). "Conditional deletion of Fgl2 specifically in mouse antigen-specific CD8+ T cells prolongs CD8+ T cell persistence, suppresses phenotypic and transcriptomic signatures of T cell exhaustion, and improves control of the tumor." (PMID 38902261, 2024). "The absence of FGL2 significantly prolonged survival in mice injected with B16F10 s.c. as well as significantly delayed tumour progression." (PMID 38191799, 2024). "In addition, the mechanism of CD16 reduction after tumor invasion also needs to be investigated, and the role of cis-binding of CD16 to FGL2 on monocytic phagocytosis needs to be further explored." (PMID 39629005, 2024). "Primary tumour burden in these mice at a single timepoint, again immediately prior to endpoint (day 14) was significantly lower in the absence of FGL2." (PMID 38191799, 2024). "MiR-20a-5p by targeting FGL2 and miR-139-5p by targeting STC1 could have an impact on tumor microenvironment by interacting with tumor-related inflammation and infiltration of macrophages and CD4+T cells." (PMID 38036953, 2023). "FGL2, FUCA1, PLEKHO1, and SIGLEC1 were highly expressed in DC and might influence its number in tumor." (PMID 35127943, 2022). "Fgl2 secreted by tumour cells can prevent the differentiation of special subgroups of CD103 dendritic cells and participate in the regulation of the immunosuppressive tumour microenvironment." (PMID 34975313, 2022).